HMGB1 (high mobility group box 1)
Diseases named in the same sentence as HMGB1 in open-access papers (continued):
Sharing a sentence is not in itself a finding about the gene and the disease.
peripheral nerve injury (8 papers, 2012 to 2023). Injury to a peripheral nerve. "Peripheral nerve injury activated a characteristic set of signaling pathways in both sexes, including HMGB1 Signaling, TREM1 signaling, IL-6 Signaling, IL-17 Signaling, Integrin signaling, HIF1α Signaling, Oxytocin Signaling, and ILK Signaling." (PMID 34966260, 2021). "The findings also advanced the HMGB1/autophagy pathway as a potential target to improve muscle atrophy in patients with peripheral nerve injury." (PMID 30526602, 2018). "The induction of HMGB1 in DRGs reportedly contributes to pain hypersensitivity following peripheral nerve injury." (PMID 23403473, 2013). "In the present investigation, we found that HMGB1 undergoes a chronic subcellular redistribution from the nucleus to the cytoplasm of primary afferent neurons following peripheral nerve injury." (PMID 22824385, 2012). "It has been reported that the induction of HMGB1 in DRGs contributes to pain hypersensitivity following peripheral nerve injury and an anti-HMGB1 neutralization antibody improves pain-related behavior induced by the application of autologous nucleus pulposus onto nerve roots in rats." (PMID 23403473, 2013). "Thus, it is possible that the anti-HMGB1 antibody could also be efficacious in attenuating peripheral nerve injury-induced pain." (PMID 23991202, 2013). "A study of SCs challenged with high mobility group box 1 (HMGB1), a DAMP passively released by necrotic cells after peripheral nerve injury, resulted in upregulation of TLR2 and RAGE mRNA in SCs." (PMID 33898462, 2021).
proliferative diabetic retinopathy (8 papers, 2011 to 2019). Advanced retinopathy due to diabetes mellitus characterized by the formation of new vessels in the retina. "In previous studies, we demonstrated that HMGB1 was upregulated in the vitreous fluid and epiretinal membranes from patients with proliferative diabetic retinopathy (PDR) as well as in the retinas of diabetic mice." (PMID 23766563, 2013). "In previous studies, we demonstrated that HMGB1 and RAGE were expressed by vascular endothelial cells and stromal cells in fibrovascular epiretinal membranes from patients with proliferative diabetic retinopathy (PDR)." (PMID 24733965, 2014).
prostate tumor (8 papers, 2015 to 2024). "Silencing RAGE in prostate tumor cells results in decreased HMGB1 expression and increased expression of death receptors DR4 and DR5, demonstrating that disruption of the HMGB1-RAGE axis induces apoptosis in prostate tumors." (PMID 38529373, 2024). "We next analysed whether mRNA expression levels of HMGB1 and its interactome partners in ovary and prostate tumours are correlated." (PMID 34572914, 2021). "For this purpose, DU145 and PC3 prostate tumor cells were cultured with 55 nM of DTX, a dose previously determined by us to cause massive cell death, after which their supernatants were collected from day 0 to day 4 for ELISA analysis of HMGB1." (PMID 26469759, 2015). "By inhibiting the HMGB1/RAGE pathway, verbascoside was shown to significantly reduce cell proliferation and migration in human prostate tumor cell lines." (PMID 36830019, 2023). "To increase our understanding of HMGB1 cellular functions in cancer cells, we profiled HMGB1 interactomes in SKOV-3 and PC-3 cancer lines from ovarian and prostate tumours, respectively, by affinity purification followed by mass spectrometry (AP-MS)." (PMID 34572914, 2021). "It was also able to inhibit cell proliferation and migration of prostate tumor cell lines, PC3 and DU-145, by suppressing the TGF-β signaling pathway and as well as the epithelial-mesenchymal transition (EMT) changes brought upon by the HMGB1/RAGE axis." (PMID 37687413, 2023). "Division of labor among these receptors do not appear to operate in prostate tumor cells, as they both could induce sCLU upon engagement of HMGB1 to drive cell survival and confer chemoresistance." (PMID 26469759, 2015). "First utilizing recombinant HMGB1, we show that it induces sCLU production from DU145 prostate tumor cells, which originally express little or no sCLU." (PMID 26469759, 2015).
Seizure (8 papers, 2015 to 2024). A seizure is an intermittent abnormality of nervous system physiology characterized by a transient occurrence of signs and/or symptoms due to abnormal excessive or synchronous neuronal activity in the brain. "Seizures cause neuronal damage, which in turn promotes the passive release of HMGB1." (PMID 39046369, 2024). "Factors that induce epileptic seizures including hyperpyrexia, injury, and infection impair astrocytes as well as microglia and subsequently induce the release of HMGB1." (PMID 31241711, 2019). "Male C57BL/6 mice were divided into four groups: normal saline control (NS) group, KA-induced epileptic seizure (EP) group, and EP group pretreated with HMGB1 (EP+HMGB1 group) or BoxA (HMGB1 antagonist, EP+BoxA group)." (PMID 26485677, 2015). "In the present study, the effect of HMGB1 on the expression of P-gp was investigated both in vivo using a KA-induced mouse seizure model and in vitro using a mouse microvascular endothelial cell line, bEnd." (PMID 26485677, 2015). "Seizures lead to brain cell damage and passive release of HMGB1, leading to a vicious cycle." (PMID 39046369, 2024). "Seizure‐induced neuroinflammation is a condition associated with the increase of cytokines such as interleukin (IL)‐1β, tumor necrosis factor (TNF), transforming growth factor (TGF)‐β, and danger signals such as High Mobility Group Box 1 (HMGB1)." (PMID 32140642, 2020).
tuberculosis (8 papers, 2015 to 2026). A chronic, recurrent infection caused by the bacterium Mycobacterium tuberculosis. "Moreover, changing effects of HMGB1 have been associated to different stages of a tuberculosis experimental model where at day 7 to 21 the oxidized HMGB1 was predominant, while during late infection only the reduced form was seen." (PMID 28178282, 2017). "HMGB1 is liberated during experimental tuberculosis and promotes or suppress the immune response and inflammation depending on the redox state." (PMID 26201072, 2015). "Thus, liberated HMGB1 during experimental tuberculosis can promote or suppress the immune response and inflammation depending on its redox state." (PMID 28178282, 2017). "It has also been demonstrated that HMGB1 acts as an adjuvant for tuberculosis subunit vaccines." (PMID 29137362, 2017). "Determine the kinetics, cellular sources and function of HMGB1 in experimental tuberculosis." (PMID 26201072, 2015). "The mean CSF HMGB1 was 19.36 ng/ml in TBM patients (n = 59) versus 3.12 ng/ml in non-TB meningitis patients (n = 30), 2.13 ng/ml in patients with extra neural tuberculosis (n = 73), and 1.06 ng/m in controls (n = 66)." (PMID 27795917, 2016).
adenoma (7 papers, 2009 to 2024). A neoplasm arising from the epithelium. "The CEA and HMGB1 cut-off points that gave the best sensitivity and specificity for the diagnosis of high-risk lesions (IM and adenoma) and cancer (EGC) were evaluated using area under the curve (AUC) analysis." (PMID 19476625, 2009). "HMGB1 nuclear expression was present in virtually all cases (> 95%), but strong nuclear expression was higher in adenomas and CRCs compared to normal mucosa." (PMID 38353760, 2024). "The rate of cytoplasmic expression of HMGB1 was higher in CRC specimens compared to adenomas (25.2 vs. 11.8%, p < 0.01)." (PMID 38353760, 2024). "Strongly positive nuclear HMGB1 rates in normal colorectal, adenoma and CRC tissue samples were 15.0% (3/20), 92.6% (63/68) and 84.0% (310/369), respectively (P < 0.01)." (PMID 33122771, 2020). "Nuclear HMGB1 expression was generally positive in normal colorectal, adenoma and CRC tissue samples, with rates of 95.0% (19/20), 98.5% (67/68) and 99.5% (367/369), respectively." (PMID 33122771, 2020). "In the present study, we quantified serum HMGB1 levels in patients who had normal gastric mucosa, IM or adenoma and carcinoma." (PMID 19476625, 2009). "However, areas of carcinoma expressed significantly stronger intensity of cytoplasmic HMGB1 compared with adjacent normal epithelium (p < 0.001) and adenoma (p < 0.002)." (PMID 36980751, 2023). "However, the sensitivity and specificity of serum HMGB1 was about 71% and 67% (cut-off value of 5 ng/ml) for the detection of cancer (EGC), and 70% and 64% (cut-off value of 4 ng/ml) for the detection of high risk lesions (IM or adenoma)." (PMID 19476625, 2009). "As reduction of nuclear HMGB1 and emergence in cytoplasmic HMGB1 expression was identified in established CRC, we investigated the expression pattern of HMGB1 throughout the adenoma–carcinoma sequence." (PMID 36980751, 2023). "However, serum HMGB1 levels tended to be elevated in patients with adenoma compared to patients with IM (data was not shown)." (PMID 19476625, 2009).
bacterial pneumonia (7 papers, 2009 to 2022). Acute infection of the lung parenchyma caused by bacteria (e.g., Streptococcus pneumoniae, Haemophilus influenzae, Chlamydia pneumoniae, Mycoplasma pneumoniae, and Legionella pneumophila). "Clinical data suggest that the increased susceptibility of alcoholics to bacterial pneumonia is due, in part, to marked increases in lung HMGB1 levels, which have been reported to be predictive of pneumococcal bacteremia." (PMID 34271850, 2021). "Previous studies investigated the role of HMGB1 in lung injury associated with Gram-negative pneumonia in mice with various comorbid conditions." (PMID 24342460, 2013). "HMGB1 plasma levels are shown to be associated with severity of the disease, survival, and mortality of bacterial pneumonia complicated by ARDS, meanwhile, treatment with HMGB1-specific antagonist revealed improved survival in preclinical animal models of acute inflammation." (PMID 35633962, 2022). "In a clinical study, mortality in patients with bacterial pneumonia complicated by ALI/ARDS was strongly predicted by initial appropriate antibiotic use and plasma HMGB-1 levels." (PMID 35204430, 2022).
brain tumor (7 papers, 2017 to 2025). "Moreover, HMGB1 released from brain tumor necrotic cells or produced by tumor-associated macrophages can recruit TREM-1+ monocytes into the tumor." (PMID 32684831, 2020). "Moreover, we expect that HMGB1 released from brain tumor necrotic cells or produced by tumor-associated macrophages can recruit TREM-1+ monocytes into the tumor." (PMID 32684831, 2020). "More specifically, tumor necrosis, a common occurrence in malignant brain tumors, begins with cell swelling and releases cytoplasmic contents such as HMGB1 into the extracellular space through plasma membrane rupture." (PMID 37210579, 2023). "In contrast, the activation of TLR2 by HMGB1 during brain tumour therapy was reported to contribute to anti-tumour immunity via activation of dendritic cells." (PMID 28300057, 2017). "In addition, we analyzed if the kind of lesion (i.e. encephalitis versus brain tumor) had an effect on protein expression levels (TLR4, HMGB1, HSP70 and NeuN) within the group of structural epilepsy." (PMID 31959173, 2020).
cervical squamous cell carcinoma (7 papers, 2016 to 2024). A squamous cell carcinoma arising from the cervical epithelium. "For monitoring disease recurrence and predicting prognosis in cervical squamous cell carcinoma patients, serum HMGB1 levels may be a helpful and precise diagnostic." (PMID 39583399, 2024). "Notably, HMGB1 expression has been reported to be related to tumor stage, invasion and metastasis in cervical squamous cell carcinoma as early as in year 2008." (PMID 33407071, 2021). "We then analyzed HMGB1 expression in two cervical squamous cell carcinomas specimens." (PMID 29472602, 2018). "The results showed that compared with the control group of cervical squamous cell carcinoma SiHa cells, the expression of differential proteins PCNA, ATM, LIG1 and HMGB1 in Ect1/E6E7 cells decreased significantly, while the expression of TDG and OGG1 proteins increased significantly." (PMID 36726132, 2023).
cholesteatoma (7 papers, 2015 to 2025). A pathologic process characterized by the proliferation of keratinizing squamous epithelium resulting in the accumulation of keratin and cells in the middle ear and/or mastoid. "The role of HMGB1 in cholesteatoma is linked to its pro-inflammatory properties." (PMID 37998605, 2023). "Given the heterogeneity of the sEV samples and also the presence of other factors in the isolated sEVs, HMGB1 might only be one of the sEV-associated factors involved in cholesteatoma pathogenesis." (PMID 37998605, 2023). "These HMGB1-enriched sEVs promoted keratinocyte proliferation and the secretion of proinflammatory cytokines such as IL-6, likely facilitating cholesteatoma progression through the activation of the MAPK p44/p42, STAT3, and NF-κB signalling pathways." (PMID 41327268, 2025). "In studies on cholesteatoma, compared with controls, sEVs isolated from patient plasma presented elevated levels of HMGB1." (PMID 41327268, 2025). "A study comparing plasma-derived small extracellular vesicles (sEVs) from cholesteatoma patients and healthy controls detected higher HMGB1 levels in the sEVs from the patient group." (PMID 39769332, 2024). "Their findings revealed a significantly elevated expression of RAGE and HMGB1 in cholesteatoma epithelium compared to normal skin." (PMID 39769332, 2024). "In the context of cholesteatoma, HMGB1(+) sEVs can exacerbate the inflammatory condition, potentially leading to tissue damage and complications." (PMID 37998605, 2023). "Semi-quantitative analysis of these blots indicated significantly increased levels of HMGB1 in plasma-derived sEVs of cholesteatoma patients relative to the normal control sEVs (fold change: 3.95 ± 1.02 and 1.00 ± 0.58, respectively; p < 0.05)." (PMID 37998605, 2023). "To summarize, research in the field of sEVs and the role of HMGB1 in cholesteatoma is continuously evolving and is considered an area of interest for understanding the disease’s pathophysiology and exploring potential therapeutic targets." (PMID 37998605, 2023). "In this study, we investigated the role of small extracellular vesicles (sEVs) in carrying HMGB1 and inducing disease-promoting effects in cholesteatoma." (PMID 37998605, 2023). "Measuring the levels of HMGB1 in lysed sEVs by ELISA revealed a statistically significant different when comparing cholesteatoma patient-derived sEVs and sEVs isolated from normal controls (p < 0.05)." (PMID 37998605, 2023). "Analogously, higher expression of HMGB1 was observed in other studies in cholesteatoma tissues or chronic middle-ear pathologies when compared to normal controls." (PMID 37998605, 2023). "HMGB1 is overexpressed in chronic middle ear pathologies and in cholesteatoma, the growth of abnormal tissue can lead to the accumulation of HMGB1 in the affected area." (PMID 37998605, 2023). "Hereby, our experiments demonstrated that levels of HMGB1 are elevated in plasma-derived sEVs from patients with cholesteatoma." (PMID 37998605, 2023). "Our data demonstrate that, in cholesteatoma patients, plasma-derived sEVs carry HMGB1 in concentrations which are higher than in sEVs isolated from plasma of normal controls." (PMID 37998605, 2023). "The receptor for advanced glycation (RAGE) and its ligand, high-mobility box 1 (HMGB1), are both known to be overexpressed in cholesteatoma and play a potential role in the pathogenesis of the disease." (PMID 37998605, 2023). "Due to the inability to create an in vivo model of cholesteatoma, we decided to perform a series of in vitro molecular studies with human keratinocytes to explore the possible role of HMGB1(+) sEVs in the pathogenesis of middle ear cholesteatoma." (PMID 37998605, 2023). "TLR4 signalling can also be induced by the DAMPs abundant in cholesteatoma tissue e.g. high-mobility group box 1 proteins (HMGB1), Tenascin, fibronectin, S100A8, S100A9 and also HSP60 and HSP70." (PMID 33627146, 2021).
cholesteatoma (continued). "Cholesteatoma samples (n = 36) and 27 normal skin specimens were studied by immunohistochemistry (IHC) for HMGB1 and RAGE expression." (PMID 25385222, 2015). "In cholesteatoma tissues, HMGB1 was also expressed in all viable and nucleated cells in the matrix and perimatrix." (PMID 25385222, 2015). "We suggest, therefore, that RAGE and HMGB1 regulate bone remodeling in chronic inflammation via up-regulation of the IL-8 production, a mediator of bone destruction, in tissue samples of cholesteatoma." (PMID 25385222, 2015). "In this study, we demonstrated for the first time co-expression of RAGE and its endogenous ligand, HMGB1, in cholesteatoma." (PMID 25385222, 2015). "Since we have not been able to establish an in vivo cholesteatoma model, we have resorted to a series of molecular in vitro studies with human keratinocytes to investigate the potential role of HMGB1 in the cholesteatoma pathogenesis." (PMID 25385222, 2015). "While all studied tissues expressed HMGB1, its expression was higher in cholesteatoma than in normal skin (p < 0.0001)." (PMID 25385222, 2015). "Of special interest is the finding of extracellular accumulations of HMGB1 in cholesteatoma tissues, suggesting that release of HMGB1 from cells and its abundance contribute to chronic inflammation." (PMID 25385222, 2015). "The data suggest that in cholesteatoma, HMGB1 released from stressed or necrotic epithelial cells and binding to RAGE overexpressed in keratinocytes initiates molecular signaling that culminates in pro-inflammatory cytokine release and chronic inflammation." (PMID 25385222, 2015). "We also observed significant differences in HMGB1 expression between normal skin and cholesteatoma tissues (p < 0.0001)." (PMID 25385222, 2015). "For this reason, responses of keratinocytes to HMGB1-induced signaling were compared to signals and expression patterns present in vivo, in the cholesteatoma tissues." (PMID 25385222, 2015). "For instance, patients with cholesteatoma exhibit higher concentrations of high-mobility group box 1 (HMGB1) carried by sEVs derived from plasma than are present in sEVs isolated from normal control plasma, suggesting their potential as a noninvasive biomarker for cholesteatoma." (PMID 41327268, 2025). "HMGB1(+) sEVs of cholesteatoma patients may also be responsible for inducing systemic inflammatory effects rather than inflammatory responses that are limited to the local temporal bone environment." (PMID 37998605, 2023). "The particle concentration was not significantly different between control and cholestatoma patients, however, western blotting of sEV protein revealed that plasma-derived sEVs isolated from cholesteatoma patients are enriched in HMGB1 in comparison to sEVs isolated from normal controls." (PMID 37998605, 2023). "However, further studies are needed to confirm and extend this aspect of HMGB1(+) sEVs in cholesteatoma." (PMID 37998605, 2023). "Based on these results, we now hypothesize that HMGB1 is also upregulated in sEVs of cholesteatoma patients." (PMID 37998605, 2023). "In this study, we analyzed plasma-derived sEVs isolated from cholesteatoma patients for the presence and quantitative assessment of HMGB1 and to determine the effect of these sEVs on cell proliferation, migration, and inflammatory cytokine production using keratinocyte cell lines." (PMID 37998605, 2023). "The study was designed to explore cholesteatoma patients’ plasma-derived sEVs concerning their morphological properties, the presence and quantitative assessment of HMGB1, and their functional effects on keratinocyte proliferation and inflammatory cytokine production using keratinocyte cell lines." (PMID 37998605, 2023). "HMGB1 levels were measured in plasma and in sEVs from cholesteatoma patients and controls." (PMID 37998605, 2023).